BRAF (B-Raf proto-oncogene, serine/threonine kinase)
Diseases named in the same sentence as BRAF in open-access papers (continued):
Sharing a sentence is not in itself a finding about the gene and the disease.
adenoma (155 papers, 2006 to 2025). A neoplasm arising from the epithelium. "Serrated tumors with MSI exhibit faster progression, and BRAF mutations are common in sessile serrated adenomas but rare in conventional adenomas, highlighting an alternative route to colon carcinogenesis." (PMID 41170468, 2025). "There is a higher prevalence of BRAF mutations in sessile serrated adenomas than in conventional adenomas, suggesting that the serrated pathway is a colorectal cancer alternative." (PMID 41323990, 2025). "BRAF V600E mutations are observed in more than 90% of all metanephric adenomas, which is more common in adults and is more often observed in adult WT as well." (PMID 39148862, 2024). "In contrast to the conventional adenoma–carcinoma pathway, the serrated pathway primarily involves two mechanisms: BRAF/KRAS mutations and CpG island methylator phenotype (CIMP)." (PMID 38515581, 2024). "KRAS mutations are found in 40% of metastatic colorectal cancer, whilst BRAF mutations are only seen in 10–15% of metastatic disease, suggesting that the adenoma-carcinoma pathway has a greater metastatic potential." (PMID 39340753, 2024). "20–30% of CRC is thought to develop through the serrated pathway, which is associated with increased MAPK/ERK pathway activity and BRAF mutations while the majority, 70–80%, is thought to develop through the adenoma pathway." (PMID 36326956, 2023). "It is worth noting that we discarded those patients with mutations in the BRAF gene, which are associated with defective mismatch repair (dMMR) and a serrated adenoma pathway." (PMID 37612734, 2023). "Among traditional serrated adenomas, BRAF mutations occur in two-thirds of the cases, but MLH1 silencing and the MSI phenotype are rare." (PMID 37190216, 2023). "The differences observed were higher frequency of APC mutations in adenomas when compared to serrated sessile lesion and hyperplastic polyp, while variants in BRAF were more prevalent in sessile serrated lesions." (PMID 35761395, 2022). "The BRAF gene mutation V600E is reported in roughly 90% of metanephric adenomas, with only 2 described cases of V600D mutation and 1 of V600K." (PMID 35198098, 2022). "We found 33.3% of our samples harboring mutations in this pathway, with mutations in the KRAS gene slightly more frequent in the adenoma group (22.4%) and BRAF predominantly present in the SSL group." (PMID 35761395, 2022). "Within this pathway, sessile serrated adenoma/polyps (SSA/P) are characterised by BRAF mutations and high levels of CpG island methylator phenotype (CIMP)." (PMID 34298598, 2021). "Considering the molecular way, the BRAF mutation is more frequent in SSAs, which is rarely present in traditional adenomas; this supports the concept that the “serrated pathway” represents an alternative route to CRC." (PMID 34205378, 2021). "Initiating APC and BRAF mutations were usually public (shared between matched adenoma and carcinoma)." (PMID 32895052, 2020). "These mutations have been identified in BRAF mutant/MSI sessile serrated adenoma and traditional serrated adenoma." (PMID 32245111, 2020). "The mutations found in the adenomas that coexisted with the PTCs in the same thyroid gland were RAS-like BRAF mutations, typical of follicular-patterned lesions, and—not surprisingly—were different from those of the PTCs to which they were associated." (PMID 32059434, 2020). "We detected a significantly low incidence of BRAF mutation in adenomas (2%) and CRC (0.7%), and a relatively low incidence of KRAS mutation (24.9%) compared with that in other populations." (PMID 31690257, 2019).
adenoma (continued). "Surprisingly, we detected a significantly low incidence of BRAF mutation, both in adenomas (2%) and in CRC (0.7%), and a relatively low incidence of KRAS mutation (24.9%) compared with that in other populations." (PMID 31690257, 2019). "This study detected a significantly low incidence of BRAF mutation in adenomas (2%) and CRC (0.7%), and a relatively low incidence of KRAS mutation (24.9%) compared with that in other populations." (PMID 31690257, 2019). "For the 98 adenoma samples, BRAF mutation was observed in two cases, with an incidence of 2% (2/98), and KRAS mutation was detected in 23 cases, with an incidence of 23.5% (23/98)." (PMID 31690257, 2019). "We also employed a ddPCR platform to seek KRAS and BRAF mutations in the plasma of patients bearing mutated adenomas." (PMID 30166531, 2018). "There was a predominance of acinar architecture (p=0.003) associated with BRAF-mutated metanephric adenomas." (PMID 28903326, 2017). "In light of the indolent clinical course and high frequency of BRAF mutation in metanephric adenomas, all cases were stained with the p16INK4 antibody." (PMID 28903326, 2017). "As expected and according with previous studies, BRAF mutations were rarely found in conventional adenomas." (PMID 28953955, 2017). "In this study, we correlated BRAF mutation, detected by molecular analysis, with BRAF V600E immunohistochemical staining in a series of 48 metanephric adenomas and 15 epithelial-predominant nephroblastomas." (PMID 28903326, 2017). "There was positive cytoplasmic immunolabeling for VE1 antibody in 33 of 41 (80%) metanephric adenomas with BRAF mutation." (PMID 28903326, 2017). "We found that BRAF-mutated cases were associated with older age whereas BRAF wild-type metanephric adenomas presented earlier." (PMID 28903326, 2017). "As expected, BRAF mutations were extremely rare in adenomas; they were found in only 0.8% of all adenomas, and in 39.4% of serrated lesions." (PMID 28953955, 2017). "Regarding metanephric adenomas, only a few studies containing overall only 20 cases, have investigated the use of immunohistochemistry to detect BRAF mutation." (PMID 28903326, 2017). "In contrast with conventional colorectal adenocarcinoma resulting from a conventional adenoma-carcinoma sequence, SACs have a higher frequency of BRAF or KRAS mutations and higher levels of CIMP." (PMID 28422723, 2017). "A series of 48 metanephric adenomas and 15 epithelial-predominant nephroblastomas were analyzed for the occurrence of BRAF mutation (BRAF V600E/V600E complex, BRAF V600D, BRAF V600K and BRAF V600R) using the BRAF RGQ PCR kit (Qiagen)." (PMID 28903326, 2017). "In summary, BRAF-mutated metanephric adenomas were associated with older age, female predominance, and the presence of a predominant acinar component." (PMID 28903326, 2017). "For the first time, we have outlined distinct morphological features characteristic of BRAF-mutated and BRAF-wild-type metanephric adenomas." (PMID 28903326, 2017). "BRAF mutation analysis was successfully performed in three of the four MACs with contiguous traditional serrated adenoma; all harbored BRAF mutations and were CIMP positive." (PMID 28422723, 2017). "Here we validate BaseScope ISMD technology and use it to map the topography of subclones bearing driver mutations in one of the KRAS, PIK3CA or BRAF proto-oncogenes in CRCs and adenomas." (PMID 29222441, 2017). "In adenomas, mutations in KRAS and BRAF occur in early to advanced adenomas in the adenoma-to-carcinoma sequence." (PMID 26910894, 2016). "In the step-wise genetic alteration model associated with colorectal tumorigenesis, PIK3CA mutations occur after KRAS or BRAF mutations and, in cooperation with other mutations, drive clonal evolution from large adenoma to invasive adenocarcinoma." (PMID 26498038, 2015).
adenoma (continued). "Another study examined intestinal adenoma, and found BRAF mutations in all (9/9) dysplastic serrated adenomas and also in 18/50 (36%) hyperplastic polyps characterized by elongated crypts." (PMID 26299805, 2015). "Clinically, SSA/Ps showing a depressed surface tend to develop in middle-aged to elderly patients, predilect for men, often occur in patients with conventional adenomas, usually arise in the proximal colon, and show BRAF-V600E mutations." (PMID 26088907, 2015). "Unlike conventional adenomas, SSPs are commonly associated with BRAF mutations; while both SSPs and conventional adenomas frequently harbor aberrantly methylated genes." (PMID 24465639, 2014). "We conclude that hypermethylation of MLH1, when occurs in an adenoma cell with BRAF oncogenic mutational activation, drives the pathway for MSI cancer by providing the cells with a mutator phenotype." (PMID 24964857, 2014). "All the pathology reports of colonic biopsies and resection specimens and slides were reviewed to ascertain the presence of serrated adenomas in the 19 cases with BRAF mutations." (PMID 25005754, 2014). "The two LST lesions with BRAF mutation were macroscopically classified as granular type and pathologically proven to be serrated adenoma." (PMID 25551625, 2014). "Constitutive activation of Wnt/β‐catenin signaling initiates the growth of benign adenomas, while mutations in KRas, BRaf, and related pathways stimulate adenoma growth and contribute to invasive and other malignant behaviors." (PMID 24963032, 2014). "Lung-specific expression of BrafV600E, the most prevalent BRAF mutation found in human tumors, results in Raf-Mek-Erk pathway activation and in the formation of benign adenomas that undergo widespread senescence in a Cre-activated Braf mouse model (BrafCA)." (PMID 24489653, 2014). "A recent study reported BRAF V600E mutation in 100% of sessile serrated adenomas/polyps, 94% of traditional serrated adenoma, and in 62% of micro vesicular hyperplastic polyps." (PMID 24298448, 2013). "In analysis of BRAF mutation status, 30/42 (73.1%) of analysed serrated adenomas were BRAF mutant, with 29/41 being V600E and 1/41 being V600L, in line with previous studies." (PMID 23671423, 2013). "Nevertheless, these results identify a tyrosinase expressing lung cell population in neonate mice where mutation of BRAF led to adenoma development." (PMID 23825589, 2013). "In the setting of BRAF mutation, these adenomas generally progress to cancer through an acquired DNA mismatch repair deficit caused by hypermethylation of MLH1 in the setting of the CpG island methylator phenotype (CIMP)." (PMID 24066160, 2013). "In the present study, the BRAF mutation frequency was 2.83% (95% CI 0.59%-8.05%) in flat adenomas and 2.15% (95% CI 0.26%-7.55%) in polypoid adenomas (p = 1)." (PMID 22848674, 2012). "Sessile serrated adenomas are more frequently found in the proximal colon, initiate through BRAF mutations and are commonly MSI." (PMID 23045412, 2012). "Of the five adenomas with a BRAF mutation, three were detected in a serrated phenotype (histologically, one was a traditional serrated adenoma (TSA) and two were sessile serrated lesion (SSL), all three were classified as a LST-F subtype)." (PMID 22848674, 2012). "An equivalent to the adenoma-carcinoma sequence has been suggested for these adenomas, of which an activating mutation in the BRAF gene is regarded as the initiating event of the malignant transformation." (PMID 22272141, 2011). "In that study, both BRAF mutation (40% versus 80%) and hMLH1 methylation (25% versus 45%) found in sessile serrated adenomas were less frequent in Korea than in the USA." (PMID 21827707, 2011). "Either KRAS or BRAF mutation was observed in 85.7% of these cases, and in 82.4% of the serrated adenomas." (PMID 21457162, 2011).
adenoma (continued). "The serrated adenocarcinoma cases presenting with a residual adenoma component undoubtedly showed KRAS mutations (57.1%) to be twice as frequent as BRAF mutations (28.6%) in serrated adenocarcinomas." (PMID 21457162, 2011). "A high combined mutation rate (79–82%) of KRAS and BRAF in serrated adenomas and adenocarcinomas indicates that mitogen-activated protein kinase activation is a crucial part of the serrated pathway." (PMID 21457162, 2011). "In a previous analysis performed in our laboratory, the 186 colorectal adenocarcinomas and 16 adenomas described in this report were tested for the presence of BRAF and K-RAS mutations." (PMID 21473780, 2011). "The type and distribution of mutations in BRAF and K-ras in the 186 adenocarcinoma and 16 adenoma tissues available from EPIC Norfolk." (PMID 20233436, 2010). "In contrast to BRAF, 6 (37.5%) adenomas harboured oncogenically activating mutations in K-ras, a prevalence consistent with previous reports." (PMID 20233436, 2010). "K-ras codons 12 and 13 and BRAF codon 600 point mutations of adenomas were analysed by direct sequencing analysis." (PMID 17923875, 2007). "Adenomas with RASSF2 methylation often carried K-ras/BRAF mutations simultaneously (22 out of 30, P<0.01)." (PMID 17923875, 2007). "Consistent with previous reports, in our study, BRAF mutation was frequently observed in serrated adenomas (5 out of 8, 63%)." (PMID 17923875, 2007). "We found that RASSF2 methylation was, like K-ras/BRAF mutations, frequently observed in large adenomas and in serrated adenomas." (PMID 17923875, 2007). "Adenomas with either K-ras/BRAF mutations, RASSF2 methylation, or both were more frequently observed in the rectum than in the distal colon (65 vs 37%, P=0.04; and 26 vs 6%, P=0.03, respectively)." (PMID 17923875, 2007). "To elucidate the differences in the contribution of the Ras signalling pathway to neoplastic development according to colonic sites, we next investigated locational distribution of adenomas with either K-ras/BRAF mutations or RASSF2 methylation, or both." (PMID 17923875, 2007). "The BRAF mutation was frequently observed in serrated adenomas and has been shown to be significantly correlated with the recently proposed serrated polyp-microsatellite instability pathway." (PMID 17923875, 2007). "The three conventional adenomas with mutations of both BRAF and KRAS were among only four adenomas that had any BRAF mutations at all." (PMID 16879389, 2006). "KRAS mutation occurred more frequently (26.5%) than BRAF mutation (4.8%) in adenomas (P < 0.001) and particularly in adenomas with villous architecture (50%)." (PMID 16879389, 2006). "BRAF-V600E is seen in over 95% of BRAF-mutated mCRC patients and is female-associated, often right-sided and advanced, mucinous, with deficient mismatch repair (dMMR) and serrated adenoma pathway mutation." (PMID 40171464, 2024). "Interestingly, using BRAF inhibitor in corticotrophic adenoma cells with a variant in the BRAF V600E gene demonstrated a decrease in ACTH production." (PMID 39512978, 2024). "Epithelial-predominant WT’s association with metanephric adenoma and BRAF V600E mutation may provide clinicians alternative treatment options." (PMID 39148862, 2024). "This evidence may suggest a common BRAF-mutated pathway which leads to epithelial WT from a metanephric adenoma origin." (PMID 39148862, 2024). "In addition, sessile serrated adenomas, which account for 6%–12% of colorectal adenomas, are characterized by high‐frequency BRAF, caudal type homeobox 2 mutations, and epigenetic abnormalities." (PMID 39054866, 2024). "MLH1 promoter hypermethylation was detected in one BRAF-mutated adenoma in our cohort." (PMID 37772997, 2023). "Additionally, the transition to the MSI phenotype via MLH1 hypermethylation is observed in approximately 75% of BRAF-mutated sessile serrated adenomas, with the remaining cases developing into MSS cancers." (PMID 37190216, 2023).
adenoma (continued). "Similarly, our CRC cases' molecular analysis revealed that the serrated pathway harboring BRAF mutation accounted for a very small percentage (2.2%), which falls behind the adenoma-carcinoma KRAS-mutated pathway (45.2%)." (PMID 35619874, 2022). "Clarifying the real-world prevalence of the BRAF V600E mutation in corticotrope adenomas may be of great importance given the existence of targeted drugs already used in several types of cancer harboring the V600E mutation." (PMID 35743266, 2022). "Serrated adenomas of the intestine that are associated with a BRAF mutation show molecular, morphological, clinical, and epidemiological characteristics that differ from those of adenomas and which develop during a “classic adenoma-carcinoma sequence” based on mutations of the APC gene." (PMID 34259881, 2021). "In fact, BRAF-driven tumours follow a different path compared to the “classical adenoma-carcinoma” hypothesis and are associated with sessile serrated adenomas." (PMID 34945008, 2021). "Furthermore, the frequency of BRAF mutation is much higher in serrated adenomas than in conventional adenomas." (PMID 31690257, 2019). "In addition, immunohistochemical analysis demonstrated that corticotroph adenomas carrying the BRAF V600E mutation had higher MAPK activity, as indicated by increased phosphorylation of Erk1/2 in these tumors compared to wild-type cases." (PMID 30093687, 2018). "The BRAF mutation is present in traditional serrated adenomas (TSAs) which are the least frequently occurring type of colorectal polyp (33-66%), but rarely in conventional adenomas (0.4-5%)." (PMID 30598662, 2018). "As in adults, BRAF mutation has been reported in pediatric metanephric adenomas." (PMID 28903326, 2017). "BRAF mutation recently has been reported in metanephric adenoma." (PMID 28903326, 2017). "Despite it having been speculated that VE1 would be valuable diagnostically, this study demonstrated that VE1 antibody is a very specific (100%) but less sensitive (80%) marker for identifying BRAF-mutated metanephric adenomas." (PMID 28903326, 2017). "In addition, we sought to identify clinical and histopathological features of metanephric adenomas harboring BRAF mutation." (PMID 28903326, 2017). "In fact, KRAS was mutated in 27% of adenomas while only 5% showed a BRAF mutation." (PMID 27902488, 2017). "The characteristic distribution of KRAS and BRAF mutations suggest there may be two different pathways in adenoma to adenocarcinoma progression." (PMID 26910894, 2016). "KRAS and BRAF mutations occur relatively early in the adenoma-carcinoma process." (PMID 26910894, 2016). "Thirdly, the observation of nuclear β-catenin in serrated adenomas that arise via BRAF mutations strongly suggests that high Wnt/β-catenin activity is favored at an early stage of serrated tumor progression via mechanisms yet unknown in human CRC." (PMID 26299805, 2015). "In contrast, the polypoid tumor with BRAF mutation was confirmed as traditional serrated adenoma." (PMID 25551625, 2014). "KRAS and BRAF mutations are nearly always mutually exclusive, and BRAF mutations are relatively rare in conventional adenomas, but closely associated with the CIMP pathway, which is found in 70–80% of all dysplastic serrated lesions of the right colon, predominantly in women." (PMID 24918610, 2014). "LST-G with BRAF mutation is more likely to be a sessile serrated adenoma." (PMID 25551625, 2014). "BRAF V600E mutation in microvesicular hyperplastic polyps might indicate the polyps that have a higher risk for progression to adenomas/adenocarcinomas." (PMID 24298448, 2013). "Traditional serrated adenomas with low and high grade intraepithelial neoplasia derived from the distal colon (19% right sided versus 67% left sided) and exhibited considerably more often KRAS mutations than sessile serrated adenomas (41% BRAF mutation versus 37 % KRAS mutation)." (PMID 23045412, 2012).